SMG1 (SMG1 nonsense mediated mRNA decay associated PI3K related kinase)
Diseases named in the same sentence as SMG1 in open-access papers (continued):
Sharing a sentence is not in itself a finding about the gene and the disease.
microcephaly (1 paper, 2022). A congenital or acquired developmental disorder in which the circumference of the head is smaller than normal for the person's age and sex. "Notably, genetic conditions causing elevated SMG-2/UPF1 phosphorylation have recently been linked to severe developmental retardation, microcephaly and variable facial and organ malformations, emphasizing the health risks associated with deregulated SMG-1 activity." (PMID 35670662, 2022).
multiple myeloma (1 paper, 2023). "A subset of cell lines, including multiple myeloma (MM) cell lines sensitive to the endoplasmic reticulum stress‐inducing compound thapsigargin, were highly susceptible to SMG1 inhibition." (PMID 36400430, 2023). "CC‐115 treatment showed a dose‐dependent increase of NMD transcripts, unfolded protein response (UPR) transcripts, and cell death via SMG1 inhibition in a subset of cell lines, primary multiple myeloma cells, and xenograft mouse models." (PMID 36400430, 2023).
synucleinopathies (1 paper, 2013). "We also provide evidence that SMG1 expression is significantly reduced in affected brain regions in at least two synucleinopathies." (PMID 24204929, 2013). "Whether SMG1 or the stress granule pathway may ultimately be exploitable for therapeutic benefit in synucleinopathies remains to be determined." (PMID 24204929, 2013). "However, if reduced SMG1 expression contributes to pathological increases in t-syn or p-syn during the course of synucleinopathies, one would predict reduced expression of SMG1 protein in brain regions affected by p-syn neuropathology." (PMID 24204929, 2013). "In this sample set, SMG1 expression was significantly reduced in DLB patients to 31.7±4.2% (p = 0.0001) of control levels, suggesting a potentially more universal role for SMG1 in synucleinopathies beyond PD." (PMID 24204929, 2013).
tongue squamous cell carcinoma (1 paper, 2021). A squamous cell carcinoma that arises from the tongue. "A previous study has developed a 16-gene prognostic signature that can predict the prognosis of patients with tongue squamous cell carcinoma, including CD96, HNF1B, and SMG1." (PMID 34322156, 2021).
viral infection (1 paper, 2022). "If it is found that pathogenic CoVs do indeed produce Z-RNA (as the ZH3 algorithm predicts) and that the RHIM in Nsp13 regulates ZBP1, RIPK3, RIPK1, TRIF or SMG1 signaling, then we suggest that effects will depend on the stage of viral infection." (PMID 35784331, 2022).
cancer (37 papers, 2012 to 2025). A tumor composed of atypical neoplastic, often pleomorphic cells that invade other tissues. "These predicted effects of SMG1 mutations (induced or reduced affinity) on our studied complex align with their prevalence in cancer genomes, proposing a structural basis for NMD dysregulation." (PMID 41189592, 2025). "Such disruptions by cancer mutations can potentially inhibit UPF1 phosphorylation by the SMG1 kinase, compromising the NMD machinery’s ability to detect PTC-containing mRNAs and eventually leading to cancer progression." (PMID 41189592, 2025). "In particular, the cancer-derived mutations within SMG1 located at 248–910 and 2200–2400 amino acids were evaluated in terms of the change in affinity or stability in the presence of SMG8/SMG9 and UPF1, respectively." (PMID 41189592, 2025). "Key protein–protein interaction (PPI) residues within the SMG1 network, which are frequently mutated in various cancers, were computationally analyzed." (PMID 41189592, 2025). "In the SMG1–SMG9 network, the cancer-derived variants in SMG1 ranging 536 aa-903 aa led to significant changes in protein–protein binding affinity." (PMID 41189592, 2025). "Cancer-derived mutations in SMG7 lack any significant effect over the interaction interface with the SMG1 or UPF2 proteins." (PMID 38542156, 2024). "Comparing the influence of cancer-derived mutations over different CLMS sites revealed that variants in the PPIs for UPF2 or SMG1 have significant structural stability effects." (PMID 38542156, 2024). "Overall, our data demonstrate that combined loss of expression of ATM and heterozygosity of SMG1 results in more rapid cancer development particularly haematopoietic cancers." (PMID 31565865, 2019). "Moreover, SMG1 dysregulation has been implicated in multiple cancer types, where it directly impacts NMD-mediated quality control, DNA repair mechanisms, and cell survival pathways." (PMID 41189592, 2025). "In addition, the effect of cancer-derived mutations in SMG1 (located within 248 aa–910 aa and 2,200 aa–2,400 aa) was characterized, and their effects on the binding affinity and stability in the presence of SMG8, SMG9, and UPF1 were predicted." (PMID 41189592, 2025). "Given that loss of SMG1 expression results in an increase in intracellular cholesterol levels, we wish to establish whether this increases cancer cell sensitivity to inhibitors of cholesterol synthesis." (PMID 35805027, 2022). "However, SMG1‐deficient animals showed elevated levels of basal inflammation and oxidative damage to tissues prior to development of cancers indicating a potential role for these pathways in enhancing tumourigenesis in this model." (PMID 31565865, 2019). "Similarly, SMG1 has been implicated in DNA damage responses and identified as a tumor suppressor linked to different cancers, stimulating interest in SMG1 as a novel target for drug therapies and a biomarker for cancer prognosis." (PMID 29192227, 2017). "However, up to date SMG1 functional mutations, deletions, or reduced expression in human cancer is rarely studied." (PMID 25257528, 2014). "Given this new physiological role for Smg-1 it will now be important to investigate whether mutations in hSMG-1 results in cell growth and/or invasiveness contributing to the aetiology of cancers." (PMID 22479207, 2012). "It is important to highlight that the SMG1+/- mice develop an auto-inflammatory phenotype in many tissues, and the persistence of this chronic multi-organ inflammation might be the cause of higher rates of cancer in the long term." (PMID 36443756, 2022). "The SMG1 kinase within the NMD machinery has a crucial role, and any alteration (cancer mutations) in it disrupts UPF1 phosphorylation, eventually resulting in improper functioning of NMD to detect mRNAs containing PTC." (PMID 41189592, 2025). "Inactive SMG1 can lead to stabilization of aberrant mRNAs, resulting in the accumulation of truncated proteins that promote cancer progression." (PMID 41189592, 2025).
cancer (continued). "To explore tumor-specific SMG-1 expression pattern among more cancers, we compared SMG-1 mRNA levels between tumor and adjacent normal tissues across 31 cancer types." (PMID 39506517, 2024). "In mice, decreased SMG1 expression levels led to increased basal inflammation and subsequent development of either cancer or chronic inflammatory disorders." (PMID 38262937, 2024). "Previous studies have demonstrated that SMG-1 has diverse expression patterns among different cancer types." (PMID 39506517, 2024). "We tested the effects of CC‐115 and SMG1i on various human cancer cell lines, focusing on hematological malignancies, as Kinome‐wide RNAi studies included SMG1 in a list of active kinases in MM models." (PMID 36400430, 2023). "Functional profiling of 141 cancer cell lines revealed inhibition of kinase suppressor of morphogenesis in genitalia 1 (SMG1), a key regulator of the RNA degradation mechanism nonsense‐mediated mRNA decay (NMD), as an additional target of CC‐115." (PMID 36400430, 2023). "Our data provide support for further clinical development of SMG1 as a therapeutic target in cancer." (PMID 36400430, 2023). "It highlights the possibility of using IL-6/STAT3/SMG1 pharmacological inhibitors to sensitize them for cancer immunotherapy." (PMID 36443756, 2022). "SMG1 is indispensable for alternative splicing of many mRNAs important during embryogenesis, and SMG1 haploinsufficiency plays roles in cancer development." (PMID 36012592, 2022). "As negative control, we employed an AS1411-control AsiC (AS1411 aptamer conjugated with control siRNA) and Scramble-SMG1 AsiC to assess that the targeting to the cancer cells was AS1411 dependent." (PMID 35991316, 2022). "In particular, the stratification of cancer patients based on tumor SMG1 expression led to survival predicted p-values of 0.0017 for PAAD, 0.0019 for LUAD and 0.0047 for BRCA." (PMID 36443756, 2022). "SMG1 upregulation by IL-6/STAT3 is exacerbated in the context of cancer immunotherapy as there are higher levels of IL-6 hampering the efficacy of the treatment." (PMID 36443756, 2022). "Serine/threonine protein kinase 1 (SMG 1) belongs to the phosphatidylinositol 3 kinase related kinase family and the knockdown expression of SMG1 can result in the inhibition of tumor cell proliferation in cancer." (PMID 31217907, 2019). "In this study, we found that the hypermethylation status of SMG1 was frequent and cancer specific in AML." (PMID 25257528, 2014). "The altered patterns of proliferation and the presence of abnormal invasive cells disrupting the epithelial-mesenchymal interactions we have observed in Smed-smg-1(RNAi) planarians are hallmarks in the early progression of most human cancers." (PMID 22479207, 2012). "Moreover, it has been reported that potentially targeting SMG1 can inhibit the NMD process that can result in triggering the immune responses in cancer through enhanced neoantigen presentation." (PMID 41189592, 2025). "In order to determine which tumor cells may be responsive to the SMG1 inhibitory effects of CC‐115, we tested various cancer cell types." (PMID 36400430, 2023). "Subsequently, the majority of the studies uncovered that MAGI2-AS3 may regulate their target genes (such as CCDC19, and SMG1) by functioning as a competing endogenous RNA for miRNAs (such as miR-15b-5p and miR-374a/b-5p) in cancers." (PMID 36998469, 2023). "Based on current knowledge, MM might be further exploited for the clinical treatment of cancer with SMG1 inhibitors." (PMID 36400430, 2023).
cancer (continued). "In addition, supporting the protective activity of NMD in cancer is the fact that haplo-insufficient SMG1+/- mice display a mildly increased of tumor incidence in older mice." (PMID 36443756, 2022). "We evaluate whether changes of SMG1 expression in malignant cells impact the immune response elicited by cancer immunotherapy." (PMID 36443756, 2022). "With this duality of function, SMG1 has emerged in recent years as a putative tumor suppressor and cancer drug target, though the relative importance of SMG1 in tumor biology remains unclear." (PMID 35805027, 2022). "To provide further evidence for SMG1 as a novel PC predisposition gene, we validated our findings in an independent case-control series consisting of 532 FPC cases (defined as ≥2 first-degree relatives with PC) and 753 non-cancer controls." (PMID 31469826, 2019). "Next, we set out to corroborate whether SMG1 suppression mediates the role of miR-18a in cancer cells." (PMID 31659158, 2019). "Taken together, these findings support SMG‐1 as a tumor suppressor gene in cancer." (PMID 29239144, 2018). "SMG1 is suggested as a novel potential tumor suppressor gene in many cancers." (PMID 29158988, 2017). "We identified that MIR7 represses SMG1 (p-value < 10-16) in cancer cells." (PMID 26897165, 2016). "A precise understanding of the mechanism(s) by which SMG-1 affects impacts growth and proliferation in physiological conditions may be important in the development of novel cancer therapies and other diseases." (PMID 22479207, 2012). "Furthermore, to evaluate how cancer-associated variants affect protein–protein or protein–mRNA networks, we systematically analyzed the mutations in core NMD components (eRF1, EIF4A3, and SMG1)." (PMID 41189592, 2025). "Thus far, the exact function by which SMG-1 participates in human carcinogenesis and treatment response remain unclear and might be cancer type dependent." (PMID 39506517, 2024). "To evaluate the role of SMG1 as the main kinase that controls the activation of NMD in different human cancers, we interrogated the TCGA dataset encompassing all cancer types with their reported survival data." (PMID 36443756, 2022). "In cancers such as microsatellite instability (MSI) cancers, NMD has been shown, on the contrary, to be activated through increased expression of certain NMD-factor genes: UPF1, UPF2, SMG1, SMG6, and SMG7." (PMID 35052820, 2022). "Given the fact that IL-6 was one of the most induced cytokines in the context of cancer immunotherapy (ICB and adoptive therapy), we wanted to evaluate whether the IL-6/STAT3 axis could in fact be upregulating SMG1." (PMID 36443756, 2022). "Focusing on the major genes in the NMD pathway (SMG1,5,6,7 and UPF1,2,3B), we first examined whether these genes were amplified in cancer." (PMID 31658270, 2019). "Interestingly, we detected higher SMG-1 expression in several cancers, including HNSCC, than in normal tissues." (PMID 39506517, 2024). "Expression of other members of RQC including Pelota, SMG1 did not correlate across cancer types, nor were patterns observed in the expression of reference genes (GAPDH, HNRPL, PCBP1, SNW1, and RER1) identified to have stable expression patterns in human cancer and matching normal cell types." (PMID 38140537, 2023).
tumor (37 papers, 2008 to 2024). "SMG1 (SMG1 Nonsense Mediated MRNA Decay Associated PI3K Related Kinase) (SMG-1), as a tumor suppressor, was significantly downregulated in GC tissues." (PMID 37386429, 2023). "In summary, we have now shown that SMG‐1 is a target of the oncomiRs, miR‐192 and ‐215, and that its downregulation is associated with tumor size and serosal invasion of GC." (PMID 29239144, 2018). "However, analyses of clinicopathologic characteristics showed that expression of SMG‐1 was negatively associated with tumor size and serosal invasion (P < 0.05)." (PMID 29239144, 2018). "In line with the hypothesis that NMD might function as checkpoint of tumor antigenicity, we interrogated the scRNAseq dataset from the study to see if higher expansion of T cells could be associated with SMG1 changes upon anti-PD-1 antibody treatment (Pembrolizumab)." (PMID 36443756, 2022). "LncRNA MAGI2-AS3 binds to miR-374b-5p and inhibits its expression, thereby playing a positive regulation part on genitalia family member-1 (SMG1), and increasing the expression levels of SMG1, which in turn plays a tumor suppressor role." (PMID 37313458, 2023). "SMG1 is a potential tumor suppressor that can antagonize mammalian target of rapamycin (mTOR) to regulate leukemia cell growth in acute myeloid leukemia." (PMID 37313458, 2023). "In line with T-cell expansion, we observed that tumors that upregulate SMG1 (+ΔSMG1) expression were characterized by a lower amount of T and B lymphocytes in the tumor milieu." (PMID 36443756, 2022). "For each tumor type in the TCGA, we established a ranking of genes from higher to lower correlation with SMG1 by Pearson analysis." (PMID 36443756, 2022). "The aptamer binds to different tumor cell lines and allows for the free uptake of siRNA cargo to inhibit the SMG1 mRNA, leading to NMD activity downregulation stabilizing encoded antigens." (PMID 35991316, 2022). "In three prevalent tumor types (BRCA, LUAD and PAAD), high expression of SMG1 was significantly associated with worse prognosis of patients." (PMID 36443756, 2022). "Subsequently, dimensionality reduction with uniform manifold approximation and projection (UMAP) was performed, followed by the separation of tumor samples based on high and low tumor-SMG1 expression in the tumor cells." (PMID 36443756, 2022). "This antitumor effect was enhanced in B16/F10 tumor-bearing mice upon systemic administration of the AS1411 SMG1 AsiC." (PMID 35991316, 2022). "This study reflected that low SMG1 tumor expression shows higher signs of T-cell activation with more CD8 effector memory function." (PMID 36443756, 2022). "Next, we looked into the average expression of SMG1, STAT3 and IL6ST only in tumor cells from each patient and we performed a correlation analysis for the expression or each factor with SMG1." (PMID 36443756, 2022). "Given the potential role of IL6ST/STAT3 axis in SMG1 regulation and the important role it might play in tumor antigenicity we interrogated the RNA expression data from TCGA repository so as to identify immune pathways that could be associated with the expression of SMG1." (PMID 36443756, 2022). "Even when patients were stratified in quartiles depending on SMG1 expression in tumor samples, those with lower tumor levels of SMG1 displayed a CD8 phenotype with more abundance of cells expressing exhaustion markers (LAG3, PD-1, CTLA-4, TIM3, TOX)." (PMID 36443756, 2022). "Only three patients with positive clonal expansion had increased levels of SMG1 upon treatment; interestingly, two of those patients (8 and 10) are precisely the ones with lower levels of SMG1 in pre-treatment tumor samples." (PMID 36443756, 2022). "We describe a broadly clinically translational aptamer RNAi AsiC to inhibit SMG1 in a wide range of tumor types." (PMID 35991316, 2022).